NF2 (NF2, moesin-ezrin-radixin like (MERLIN) tumor suppressor)
Diseases named in the same sentence as NF2 in open-access papers (continued):
Sharing a sentence is not in itself a finding about the gene and the disease.
kidney cancer (3 papers, 2016 to 2022). Primary or metastatic malignant neoplasm involving the kidney. "Merlin/neurofibromatosis type 2 (NF2) is a tumor suppressor, and the Merlin/NF2 mutation is the cause of the development of kidney cancer." (PMID 35910387, 2022). "The importance of YAP/TAZ signalling in NF2 loss kidney cancer was further assessed using ACHN and LB996-RCC cells, two NF2 loss, nccRCC cell lines." (PMID 27713405, 2016).
kidney tumors (3 papers, 2023 to 2025). "A study that performed a comprehensive genomic profiling (CGP) of over 3900 clinically advanced kidney tumors found that 192 (4.9%) RCC tumors had NF2 mutations." (PMID 39796693, 2024). "In conclusion, the present study is the largest to characterize genomic findings in NF2-mutated kidney tumors." (PMID 36917021, 2023). "Genomic alterations (GA) in NF2 tumor-suppressor gene have been associated with aggressive behavior in kidney tumors." (PMID 36917021, 2023). "In the TCGA validation cohort, 35/1486 (2.4%) kidney tumors harbored NF2 GA and 37 types of different mutations were seen." (PMID 36917021, 2023). "In this study, we characterized the genomic landscape of NF2-mutated kidney tumors in a large cohort of 3919 cases." (PMID 36917021, 2023). "Clinical, molecular, and immune biomarkers in NF2-mutated kidney tumors." (PMID 36917021, 2023). "A study using an inducible orthotopic kidney tumor model found that YAP/TAZ silencing induces regression of established NF2-mutant tumors, prolonging survival in mice with NF2-mutant RCC." (PMID 39796693, 2024). "In this study, comprehensive genomic profiling (CGP) was used to evaluate the frequency of NF2 genomic alterations in histologic subtypes of kidney tumors and co-occurring genomic alterations in other genes and biomarkers." (PMID 36917021, 2023). "We used comprehensive genomic profiling (CGP) to evaluate the frequencies of NF2 GA in histologic subtypes of kidney tumors and co-occurring GA in other genes and biomarkers." (PMID 36917021, 2023). "Similar studies, including consecutive unselected cases of kidney tumors, are needed to further characterize RCCs harboring NF2 GA." (PMID 36917021, 2023). "Intriguingly, YAP has also been found to promote glycolysis in NF2-mutant kidney tumors." (PMID 40707702, 2025). "One hundred ninety-two of kidney tumors featured NF2 GA (4.9%), while 3727 (95.1%) did not." (PMID 36917021, 2023).
leukemia (3 papers, 2013 to 2025). A malignant (clonal) hematologic disorder, involving hematopoietic stem cells and characterized by the presence of primitive or atypical myeloid or lymphoid cells in the bone marrow and the blood. "MN1 and NF2 have previously been implicated in the development of leukemia and solid tumors, and ZNRF3 and KREMEN1 are inhibitors of the Wnt/beta-catenin signaling pathway." (PMID 24236197, 2013).
Meningothelial Meningioma (3 papers, 2018 to 2025). A WHO grade I meningioma characterized by the presence of tumor cells that form lobules. "Our study only found AB-P immunoreactivity to be significantly higher in meningothelial meningiomas, as could be explained by NF2 mutations being less common in meningothelial meningiomas." (PMID 40447281, 2025). "Interestingly, both NF2 and NHERF1 showed higher cytoplasmic expression in the secretory component of mixed secretory-meningothelial meningioma." (PMID 29983887, 2018).
meningothelial tumors (3 papers, 2013 to 2025). "To this end, we generated 2 cell lines from IOMM-Lee cells, an immortal, NF2 wildtype line of meningothelial tumor cells, with a lentivirus carrying KLF4wt or KLF4K409Q with a BSD-tag (BSD selectable marker) under the control of an EF1-α promoter." (PMID 32245394, 2020).
Parkinson disease (3 papers, 2018 to 2025). A progressive degenerative disorder of the central nervous system characterized by loss of dopamine producing neurons in the substantia nigra and the presence of Lewy bodies in the substantia nigra and locus coeruleus. "The identification of CASP1 and HTRA2, a mitochondrial serine protease mediating apoptosis in Parkinson’s disease, also highlights the important role of caspase-dependent apoptosis in merlin-deficient Schwann cells in an in vitro model of NF2." (PMID 32848608, 2020).
peripheral nerve schwannoma (3 papers, 2021 to 2025). A benign, usually encapsulated slow growing tumor of the peripheral nervous system composed of Schwann cells. "The management of peripheral nerve schwannomas associated with NF2 and SWNT is complex due to multiplicity and comorbidities, prompting for interdisciplinary care." (PMID 35771312, 2022).
sensorineural hearing loss (3 papers, 2018 to 2023). "Using this established model of NF2, we tested the hypothesis that chemopreventative COX-2 inhibition attenuates spontaneous schwannomagenesis or sensorineural hearing loss (SNHL)." (PMID 29416648, 2018).
tumor syndrome (3 papers, 2016 to 2025). "Perioperative comparison of both tumor syndromes showed more neurological deficits (p = 0.027), and less pain (p = 0.024) in NF2-associated tumors." (PMID 35771312, 2022).
Von Hippel Lindau syndrome (3 papers, 2019 to 2025). "Syndromic association was found in 12 cases (2.2%), neurofibromatosis type 2 (NF2) was detected in eight, and Von Hippel-Lindau syndrome in four cases." (PMID 39229481, 2024).
anaplastic thyroid cancers (2 papers, 2014 to 2025). "NF2 mutations have also been discerned in 18% (two of 11) anaplastic thyroid cancers." (PMID 24393766, 2014).
aneurysm (2 papers, 2018 to 2020). Bulging or ballooning in an area of an artery secondary to arterial wall weakening. "This fact of a younger age at rupture is of note and can be interpreted as a higher vulnerability of aneurysms in NF2 patients for rupture compared to the general population." (PMID 30250447, 2018).
bladder cancer (2 papers, 2021 to 2023). "Normal cells derived exosomes could regulate NF2 to inhibit tumor growth and progression of bladder cancer." (PMID 37805491, 2023). "For example, in bladder cancer, miR-146b-3p can expedite proliferation and invasion of cancer cells via targeted down-regulation of 15-hydroxyprostaglandin dehydrogenase (HPGD) and neurofibromin 2 (NF2) expressions." (PMID 34115567, 2021).
brain cancer (2 papers, 2012 to 2025). A primary or metastatic malignant neoplasm affecting the brain. "They concluded that NF-2 patients had a 14-fold increased risk of developing malignant brain tumor after radiation." (PMID 22829840, 2012).
cardiac failure (2 papers, 2018 to 2021). "Finally, we have also detected a significant association between rare variants in NF2 and Heart Failure (p = 1.0E−06)." (PMID 34302027, 2021).
COVID-19 (2 papers, 2021 to 2022). A disease caused by infection with severe acute respiratory syndrome coronavirus 2. "The comparison “control vs. case” recognized 269 differentially expressed proteins, of which the down-regulation of neurofibromin 2 (NF2) was proposed as a specific plasma biomarker for COVID-19." (PMID 35269564, 2022). "The “control vs case” analysis identified 269 proteins as significantly differentially expressed in COVID-19 patients, with the NF2 protein identified as the most perturbed (FDR p-value = 1.31E−86, logFC = − 4.62E + 00)." (PMID 33737684, 2021). "Neurofibromin 2 (NF2) was identified as the most perturbed protein in this study and regardless of disease severity, was significantly down-regulated in all COVID-19 patients." (PMID 33737684, 2021).
developmental delay (2 papers, 2012 to 2022). "According to Halliday, developmental delay is observed in about 3% of NF2 children—only two NF2 cases with 22 chromosome microdeletions of undefined extents, one displaying ring chromosome 22 and another with a mild delay and a small intragenic lesion, have previously been reported." (PMID 36077416, 2022). "A second patient (p41) had NF2, facial dysmorphic features, mental retardation, developmental delay and a large 22q12 deletion with unknown span due to an unclear proximal deletion breakpoint." (PMID 22436304, 2012).
Epiretinal membrane (2 papers, 2018 to 2025). An epiretinal membrane is a thin sheet of fibrous tissue on the surface of the retina along the inner limiting membrane. "Although the association of NF2 with sub-lenticular cataracts has long been appreciated, other non-neoplastic ophthalmologic manifestations of NF2, such as orbital hamartoma and epiretinal membranes also occur more frequently than in the general population." (PMID 30356733, 2018).
Familial adenomatous polyposis (2 papers, 2011 to 2017). Familial adenomatous polyposis (FAP) is characterized by the development of hundreds to thousands of adenomas in the rectum and colon during the second decade of life. "Mutation position and type of mutation have been shown to affect phenotype for a number of tumour-prone disorders including neurofibromatosis type 2 (NF2) and familial adenomatous polyposis." (PMID 21152126, 2011).
glial cell tumours (2 papers, 2015 to 2017). "Together with the well-recognized role of NF2 in glial cell proliferation in some human malignant gliomas, these findings indicated that increased expression of DNMT1 might promote the development of GBM by decreasing the expression of NF2 through methylation." (PMID 28764788, 2017).
Intellectual disability (2 papers, 2022). "Patients 366 and 160 both showed intellectual disability, which is unusual in the NF2 phenotypic spectrum." (PMID 36077416, 2022).
liposarcoma (2 papers, 2018 to 2019). A usually painless malignant tumor that arises from adipose tissue. "EGFR (R108K) and NF2 (K20*) were the two possible driver mutations that were detected in 2 separate samples and have not been described before in WD/DD liposarcoma." (PMID 29731991, 2018).
liver fibrosis (2 papers, 2017 to 2024). "Combined with these, we demonstrate that SNHG5 has pro-fibrotic potency and that SNHG5 can regulate the Hippo pathway-mediated EMT process in liver fibrosis through binding to NF2." (PMID 38438584, 2024). "Our results suggest that SNHG5 induces Hippo-mediated EMT processes, at least in part, by interacting with NF2, and that this is an interesting mechanism for regulating liver fibrosis." (PMID 38438584, 2024).
malignant meningioma (2 papers, 2015 to 2021). "NF2-null malignant meningioma KT21-MG1-Luc5D cells (hereafter referred to as KT21), were stably transduced with either empty virus or a virus encoding a Pak1 or Pak2 shRNA construct." (PMID 25596744, 2015). "Chrysophanol may be useful as a treatment against malignant meningioma by inhibiting OGN/mTOR signaling and activating NF2 signaling." (PMID 33622177, 2021).
Meningioangiomatosis (2 papers, 2010 to 2020). A rare vascular malformation in the cerebral cortex and overlying leptomeninges. "Meningioangiomatosis is rare poorly understood lesion, with approximately 200 cases described in the literature, which has been associated with NF2." (PMID 31161239, 2020). "Interestingly, despite the strong association of meningioangiomatosis and NF2, and the presence of germline NF2 mutations in cases of NF-associated meningioangiomatosis, sporadic lesions do not typically demonstrate mutations in NF2." (PMID 31161239, 2020). "Subsequent studies showed that meningioangiomatosis was instead associated with NF2." (PMID 31161239, 2020). "NF2-associated meningioangiomatosis is often asymptomatic and diagnosed only at autopsy." (PMID 20565869, 2010). "Some studies revealed that loss of 22q12 (NF2 gene) in an each case of meningioangiomatosis and meningioangiomatosis-associated meningioma indicated the possibility of which meningioangiomatosis may be neoplastic in nature." (PMID 20565869, 2010). "In at least one case report, a patient developed a malignant SMARCB1-deficient desmoplastic spindle cell sarcoma associated with pre-existing sporadic meningioangiomatosis in the absence of germline SMARCB1 or NF2 mutations." (PMID 31161239, 2020). "Meningioangiomatosis may occur either sporadically or occur in patients with neurofibromatosis type 2 (NF2)." (PMID 20565869, 2010). "However, recent large genetic series demonstrated that there was no NF2 gene mutation either in sporadic or NF2-associated meningioangiomatosis." (PMID 20565869, 2010).
multiple endocrine neoplasia type 1 (2 papers, 2022 to 2024). An autosomal dominant tumor predisposition syndrome caused by pathogenic variants in the MEN1 gene, characterized by an increased risk of tumors of the parathyroid glands, pituitary gland, and foregut neuroendocrine tumors (most commonly pancreatic islet cells). "Although their increased incidence has been reported in certain cancer‐prone diseases, such as neurofibromatosis type 2 (NF2), multiple endocrine neoplasia type 1 (MEN1) syndrome, and Turcot syndrome, they mostly occur as sporadic events with a poorly characterized genetic risk." (PMID 35689525, 2022).
non-small cell lung carcinoma (2 papers, 2012 to 2018). A group of at least three distinct histological types of lung cancer, including non-small cell squamous cell carcinoma, adenocarcinoma, and large cell carcinoma. "A study has found that 38% of MPM samples displayed NF2 gene mutations, and 29.4% displayed deletions, while no NF2 mutations were found in non-small cell lung cancer patients." (PMID 29666782, 2018).
optic atrophy (2 papers, 2025). A disorder characterized by loss of optic nerve fibers. "This case highlights the systematic approach to a case of optic atrophy in a child and identifying the rare etiology of optic nerve calcification with a report of novel variant in NF2 gene." (PMID 40236506, 2025). "•Optic atrophy accompanied by optic nerve and choroidal calcification may be a presenting feature of NF2." (PMID 40236506, 2025).
optic nerve tumors (2 papers, 2018 to 2025). "In addition, NF2 can also cause optic disc swelling, macular lesions, macular dragging, focal choroidal excavation, optic nerve tumors, and other optic nerve-related abnormalities." (PMID 40852360, 2025).
papillary thyroid cancer (2 papers, 2016 to 2020). "It has been advocated that chromosome 22q loss is associated with loss of NF2 and CHEK2 tumor suppressors and is influential in the carcinogenesis of papillary thyroid cancer." (PMID 32380731, 2020). "Loss of chromosome 22 locus for NF2 is a frequent event in papillary thyroid carcinoma, explaining that two such tumors lacked NF2." (PMID 27229317, 2016).
pilocytic astrocytoma (2 papers, 2018 to 2020). Pilocytic astrocytoma is a rare subtype of low-grade glioma of the central nervous system characterized by a well circumscribed, often cystic, brain tumor with a discrete mural nodule and long, hair-like projections that extend from the neoplastic astrocytes. "Diffuse astrocytomas and pilocytic astrocytomas are uncommonly observed in patients with NF2, but the causal association of these lesions with NF2 is unclear." (PMID 31161239, 2020).
polyneuropathies (2 papers, 2014 to 2018). "Gene dosage effects are well known for Nf2 since loss of heterozygosity in NF2 patients often causes tumor formation and/or polyneuropathies." (PMID 29715273, 2018). "Furthermore, NF2-associated polyneuropathy typically involves more than two peripheral nerves and predominantly affects extremities in a distal and symmetric fashion, suggesting a systemic rather than local issue." (PMID 25012216, 2014). "In single NF2 patients, polyneuropathy even developed years before other NF2-related symptoms, like tumors, became evident." (PMID 25012216, 2014). "This is consistent with clinical findings that NF2 germline mutations are sufficient to cause polyneuropathy; the loss of the second allele is not required in humans." (PMID 25012216, 2014). "Focusing on the pathogenesis of polyneuropathy affecting NF2 patients, Sperfeld and colleagues also suggested that the nerve damaging disease could possibly occur because Schwann cells can no longer adhere properly to the axons." (PMID 25012216, 2014). "Both neuropathological and electrophysiological investigations initially suggested that NF2-related polyneuropathy might develop independently of large solitary schwannomas." (PMID 25012216, 2014). "Concretely, in some NF2 patients suffering from polyneuropathy, muscle weakness occurs without significant spinal or peripheral nerve tumor burden, suggesting that factors other than gross tumor growth might be responsible for this disorder." (PMID 25012216, 2014).
RASopathies (2 papers, 2019 to 2023). "Further analysis of the exome data for this patient did not reveal any variants in SPRED1, NF2 or other genes associated with RASopathies that could explain the phenotype." (PMID 37012328, 2023).
Secretory Meningioma (2 papers, 2018 to 2025). A WHO grade I meningioma characterized by the presence of epithelial differentiation and numerous intracellular PAS positive bodies that are rich in glycogen. "As in secretory meningioma, moesin but not NF2 appeared to be expressed with NHERF1 in the dot-like structures." (PMID 29983887, 2018).
Sepsis (2 papers, 2024 to 2025). Sepsis is defined as life-threatening organ dysfunction caused by a dysregulated host response to infection. "In conclusion, FGF15 suppresses M1 macrophage polarization and associated inflammatory responses in sepsis by activating the NF2-Hippo pathway, thereby inhibiting H3K18 lactylation-driven Irf7 expression." (PMID 40825908, 2025). "Our results also identified a site in neurofibromin 2 (Nf2), which showed significant DRE in the hippocampus in both CLP-induced and LPS-induced sepsis." (PMID 39135964, 2024).
Stroke (2 papers, 2018 to 2020). Sudden impairment of blood flow to a part of the brain due to occlusion or rupture of an artery to the brain. "The young age from 2 to 22 years of all 6 stroke patients and the occurrence in a distinct anatomical area make a genetic influence of the NF2 mutation likely in the pathophysiology of these ischemic insults." (PMID 30250447, 2018). "None of the patients was previously diagnosed for NF2, none of them had any cardiovascular risk factors and cardiac, vascular and laboratory diagnostic was inconspicuous for extracranial stroke reasons." (PMID 30250447, 2018).
teratoma (2 papers, 2019 to 2025). A non-seminomatous germ cell tumor characterized by the presence of various tissues which correspond to the different germinal layers (endoderm, mesoderm, and ectoderm). "Indeed, we identified up to 26 and 2 (FUS and NF2) loci when reprogrammed cells were produced with Lentiviral and Sendai methods respectively and no cancer associated-gene locus variations were found in teratoma generated with mRNA-derived hiPSCs." (PMID 31105870, 2019).
thyroid (2 papers, 2018 to 2021). "In recent years, several studies identified genes that cooperate with RAS mutations in the pathogenesis or progression of thyroid and other types of cancers, such as NF1, APC, PTEN, KEAP1, NF2 and others." (PMID 34065786, 2021).
adenoma (1 paper, 2019). A neoplasm arising from the epithelium. "Among the proteins of interest identified in adenomas were moieties associated with growth-regulating pathways; i.e. NF2 (merlin), BRCA-related protein, members of the histone 1 family and olfactomedin-4." (PMID 30995271, 2019). "NF2, a potent inhibitor of HIPPO signaling, was strongly up-regulated by Aquamin in adenoma colonoids." (PMID 30995271, 2019).